VIM (vimentin)
Diseases named in the same sentence as VIM in open-access papers (continued):
Sharing a sentence is not in itself a finding about the gene and the disease.
ovarian carcinoma (continued). "Thus, we first confirmed that TGF-β1 treatment was able to enhance the ovarian cancer cell EMT in vitro by assessing the tumor cell morphology and expression of EMT markers (E-cadherin and vimentin)." (PMID 35800071, 2022). "Furthermore, the combination of citrullinated VIM and ENO1 peptides in a vaccine, designated Modi-1, induced a significant antitumoral response in a mouse model of ovarian cancer." (PMID 36291752, 2022). "In addition, it was confirmed that PARD6A regulated the migration and invasion of ovarian cancer cells through regulating important molecules in EMT pathways such as SNAIL1, E-cadherin, and VIMENTIN." (PMID 35379775, 2022). "TGF-β1 treatment enhanced ovarian cancer cell epithelial–mesenchymal transition (EMT), whereas sorafenib and a selective TGF-β1 inhibitor Ly2157299 reversed tumor cell EMT, invasion, and expression of EMT markers (E-cadherin and vimentin)." (PMID 35800071, 2022). "When mRNA levels of SNAIL1, E-cadherin, and VIMENTIN were demonstrated to be affected by PARD6A expression, it was indicated that PARD6A likely affects EMT of these ovarian cancer cells through regulating SNAIL1 signaling pathway, thus acting on the downstream E-cadherin and VIMENTIN." (PMID 35379775, 2022). "In the current study, we first established a cell model of TGF-β1-induced ovarian cancer cell EMT and found that sorafenib was able to increase the protein level of E-cadherin and suppress the protein expression of vimentin, indicating that sorafenib reversed the effect of TGF-β1." (PMID 35800071, 2022). "Ten-eleven translocation 1 (TET1), an important DNA demethylase, was found to be overexpressed in cisplatin-resistant ovarian cancer cells and could induce partial EMT by increasing vimentin expression through demethylation of the vimentin promoter." (PMID 36313710, 2022). "Additionally, the positive correlation between HK2 and fibronectin, MMP9, CHD2, Vimentin, ZEB1 and ZEB2 in human ovarian cancer were confirmed from the GEPIA online database (p < 0.05)." (PMID 35953860, 2022). "After ovarian cancer cells were treated with WZ10, there was a dose-dependent, significant downregulation in the expressions of cyclin, Oct-4 and vimentin, suggesting that WZ10 treatment could inhibit the activation of the Hippo-YAP pathway." (PMID 36498794, 2022). "Protein expression levels of E-cadherin, VIMENTIN, ZO-1, TWIST-1 and PAR6α were assessed in total protein lysates and protein expression levels of SNAIL1 were assessed in nuclear lysates, respectively, in multiple ovarian cancer cell lines." (PMID 35379775, 2022). "Besides, we observed that ectopic LINC00909 in OVCAR4 cells decreased E-cadherin and increased N-cadherin/vimentin expression, demonstrating that it promotes epithelial-to-mesenchymal transition (EMT) of ovarian cancer cells." (PMID 34336102, 2021). "Hence, we determined that ITGB6-mediated TGFβ activation is involved in regulating the expression of N-cadherin, Snail, Vimentin and E-cadherin and promoting EMT progression in ovarian cancer spheroids." (PMID 34621667, 2021). "Our results indicated that the knockout of the EGFL6 gene could inhibit EMT in ovarian cancer cells by upregulating the expression of E-cadherin and downregulating the expression of N-cadherin, MMP2, MMP9, and Vimentin." (PMID 32983976, 2020). "Budding of ovarian cancer spheroids from monolayers correlated with the expression of vimentin and lack of cortical E-cadherin." (PMID 32033410, 2020). "Western blot analysis revealed a similar pattern of TRPM7, E-cadherin, Vimentin and Twist expression in some ovarian cancer and non-tumor tissues." (PMID 30819230, 2019). "The two non-epithelial ovarian cancer cultures were pancytokeratin-negative, but expressed CA125 and vimentin, which was in keeping with their diagnostic tumour immunohistochemistry; thus, they were also included for HRR analysis." (PMID 30871186, 2019).
ovarian carcinoma (continued). "However, E-cadherin and vimentin expression remained unchanged in daidzein and ERB-041 treated ovarian cancer cells." (PMID 29743815, 2018). "Here, we designed small-scale siRNA screens targeting these six mesenchymal signature genes (CD99L2, EMP3, ITGA5, SYDE1, VIM, ZEB1) to explore their functional relevance and their roles during EMT reversal by nintedanib (BIBF1120) in a mesenchymal-like SKOV3 ovarian cancer cell line." (PMID 26061747, 2015). "Advanced stages of ovarian cancer involve a mechanism called epithelial mesenchymal transition (EMT) in which epithelial cancer cells lose cytokeratin expression but gain mesenchymal markers such as N-cadherin and vimentin to facilitate metastasis." (PMID 23460878, 2013). "Furthermore, our analysis of the ovarian cancer data indicates that E2F1, and direct downstream targets of the WNT pathway (survivin, ID2 and vimentin) critical in cell-cycle progression, are up-regulated." (PMID 22548828, 2012). "Notably, most cells stained for EpCAM, CD44, and vimentin, suggesting that EpCAM/CD44 signals underestimate the phenotypic diversity within early passage ovarian cancer cells." (PMID 21264259, 2011). "Immunohistochemical staining of vimentin (VIM), CD45, and cytokeratin-7 (CK7) was also performed on tumor tissues from metastatic and primary tumors belonging to different ovarian cancer histotypes to investigate the fractions of the major cell lineages in these tumors." (PMID 38328306, 2023). "Furthermore, resistin accelerates the EMT process in ovarian cancer cells by decreasing the expression of the epithelial cell marker E-cadherin and boosting the expression of the mesenchymal cell markers ZEB1 and Vimentin, thereby encouraging cancer cells to migrate." (PMID 36694280, 2023). "As downstream targets of the TGFβ1/SMAD3 pathway and essential participants in EMT promotion, N-cadherin, Vimentin, E-cadherin and Snail were found to be regulated by SMYD3 and ITGB6 and could contribute to enhanced invasion and adhesion in ovarian cancer spheroids." (PMID 34621667, 2021). "Finally, similar patterns of TRPM7, E-cadherin, Vimentin and Twist expression were observed in ovarian cancer cells and non-tumor ovarian epithelial cells." (PMID 30819230, 2019). "Therefore, in ovarian cancer cells with intermediate phenotypes, GRHL2 overexpression resulted in partial MET from an intermediate mesenchymal towards an intermediate epithelial state, with the co-expression of E-cadherin and vimentin." (PMID 31372511, 2019). "Moreover, it was found by western blot assay that the action of CE significantly elevated the expression of E-Cadherin protein, while the protein expression of N-Cadherin and Vimentin was reduced, which indicated that CE could inhibit the EMT process of ovarian cancer cells." (PMID 40071097, 2025). "Moreover, this study demonstrated that the small subpopulation of stem-like, tumor-propagating ovarian cancer cells were earmarked by expression of cluster of differentiation 44 (CD44) and other stem cell and EMT markers such as KIT (CD117), SCF (stem cell factor), SLUG (SNAIL2), and VIM (vimentin)." (PMID 31614568, 2019). "Very similar populations of cells were positive for vimentin, an important marker of EMT; therefore, we suggest that these two populations of cells are putative stem cells, which might be involved in the epithelial-mesenchymal transition and the manifestation of ovarian cancer." (PMID 28231820, 2017).
ovarian carcinoma (continued). "Similarly, we observed increased levels of the epithelial marker E-cadherin and reduced amounts of mesenchymal markers, including vimentin and N-cadherin, upon ISL treatment, indicating that ISL at a noncytotoxic concentration led to a robust MET in ovarian cancer cells." (PMID 31623144, 2019).
colon carcinoma (157 papers, 1994 to 2026). "Vimentin deficiency leads to accelerated and increased tumorigenesis in this colitis-associated colon cancer model." (PMID 35399505, 2022). "Our studies show that as a result of TUBB4B protein decrease, which causes microtubule decomposition, the interaction between vimentin and microtubules is augmented in the invasive colon cancer cells." (PMID 31375012, 2019). "Vimentin is the predominant intermediate filament protein in mesenchymal cells, and is implicated in metastasis and cancer cell migration in breast and colon cancer cell lines." (PMID 31272261, 2019). "In this regard, we have previously demonstrated that MEK5/ERK5 activation is associated with upregulation of the mesenchymal marker vimentin, promoting colon cancer cell invasive and metastatic behavior in an orthotopic xenograft model." (PMID 30774996, 2019). "FoxM1-mediated colon cancer metastasis is linked to regulating E-cadherin, vimentin, Snail expressions." (PMID 26755651, 2016). "The expression levels of Wnt3a and EMT-associated proteins (E-cadherin, vimentin, and β-catenin) were assessed by immunohistochemistry in human colon cancer tissues to evaluate the clinicopathological significance of Wnt3a, as well as the correlation between Wnt3a and EMT." (PMID 25499541, 2014). "Previous studies in lung- and colon cancer reported that increased vimentin expression was connected with metastasis, shorter survival, and affected lymph nodes." (PMID 40558484, 2025). "CircITGB6 enhance the mRNA stability of PDPN by directly binding to IGF2BP3, thereby promoting EMT progression in colon cancer cells by regulating the expression of E-cadherin, N-cadherin, and Vimentin." (PMID 40109856, 2025). "In experimental models of colon cancer, the downregulation of vimentin expression by miRNA-17-5p was found to inhibit EMT and metastasis 59,60." (PMID 40083939, 2025). "Millimolar levels of ascorbate inhibited the expression of the EMT-related protein Snail, Vimentin, and N-cadherin expression in breast, pancreatic, and colon cancer cells and mouse models 52-54." (PMID 39990670, 2025). "VATANST peptide (STP) emerged as specific for colon cancer targeting since it binds to vimentin, which is highly expressed on the surface of colon cancer cells." (PMID 38543324, 2024). "Knockdown of SERPINC1 in colon cancer cells inhibited TGFβ‐induced high expression of VIM, while knockdown of SERPINC1 in colon cancer cells restored TGFβ‐induced reduction of Cdh1 expression." (PMID 38923313, 2024). "Vimentin plays an important role in suppressing intestinal inflammation involved in colon cancer development." (PMID 37371778, 2023). "The upregulation of NIBP expression in colon cancer seemed to inhibit the expression of E-cadherin, whilst the expression of vimentin and CD44 remained high." (PMID 36765706, 2023). "Previous studies have shown that vimentin knockdown impaired cell attachment, migration, and invasion in breast and colon cancer cell lines." (PMID 36631457, 2023). "Our study focused on the specific molecular mechanism of ARID1A in colon cancer proliferation and metastasis via VIM/CDH dysregulation." (PMID 36420658, 2022). "MIR503HG regulates the expression of Par4 through spongy miR-107 to inhibit colon cancer cell proliferation, migration and invasion, promote cell apoptosis, down-regulate N-cadherin and Vimentin, and up-regulate E-cadherin." (PMID 35771155, 2022). "Knockdown of ZFAS1 can lead to a less aggressive phenotype in colon cancer cell lines, reduction in the mesenchymal marker vimentin, and an increase in the epithelial marker E-cadherin." (PMID 33771981, 2021). "Constitutive activation of ERK5 resulted in an increase in the nuclear accumulation of NF-kB-mediated upregulation of vimentin expression, and an increase in cell cycle progression and cell migration in colon cancer cells." (PMID 33572742, 2021).
colon carcinoma (continued). "The co-culture of colon tumor organoids with this population of CAFs resulted in the upregulation of vimentin and ZEB1 in tumor cells." (PMID 34680267, 2021). "The peptide VATANST (STP) can specifically bind with vimentin highly expressed on the surface of colon cancer cells, thus achieving the tumor-targeting effects." (PMID 34721033, 2021). "The intrinsic ability of plant viruses to target specific mammalian cells is not obvious; however, CPMV spontaneously binds to cervical and colon cancer cells through vimentin, a cell marker expressed also on GBM." (PMID 34638864, 2021). "Prior studies found that HMGA1 regulates mesenchymal genes in colon cancer cells, such as Vimentin (VIM), N-cadherin (CDH2), E-cadherin (CDH1), and Fibronectin (FN1)." (PMID 34572547, 2021). "The images obtained with a confocal microscope show a reduction in the fluorescence levels of the Vimentin and phospho-Paxillin proteins, confirming the beneficial role of GSEs on the inhibition of colon cancer progression." (PMID 32143529, 2020). "LncRNA ZFAS1 accelerates the EMT process via the induction of ZEB1 expression, while knockdown of ZFAS1 upregulates the expression of E-cadherin and ZO-1, but decreases that of ZEB1, vimentin and N-cadherin in colon cancer cells." (PMID 33246471, 2020). "EMT is critical for cell motility of colon cancer and E-cadherin, N-cadherin, Vimentin and Snail are the markers of EMT." (PMID 33063817, 2020). "The ELN recombinant protein also induces α-SMA and VIM proteins, but reduces E-cadherin in colon cancer epithelial cells." (PMID 32171282, 2020). "The expression of E-cadherin and vimentin is considered of high reference value in the prognosis of colon cancer." (PMID 33013406, 2020). "In this regard, we found that TYW2 CRISPR/Cas9-mediated deletion in both HCT-116 and SW480 colon cancer cells induced down-regulation of E-cadherin and up-regulation of vimentin." (PMID 32778592, 2020). "To gain a deeper understanding on the mechanism of how ADAMTS6 affects cell growth and motility of colon cancer cells, we tested the protein levels of E-cadherin, N-cadherin, Vimentin and Snail by western blotting." (PMID 33063817, 2020). "In colon cancer, this miRNA reduces the expression of vimentin and increases the expression of E-cadherin, favoring the generation of a stable epithelial phenotype, with reduced cellular migration and invasion." (PMID 32094378, 2020). "Asiatic acid can also affect the expression of epithelial-mesenchymal transition marker proteins in colon cancer cells (E cadherin↑, vimentin ↓, N-cadherin↓), achieved this anti-cancer potential by regulating PI3K/Akt/mTOR/p70S6K signaling pathway." (PMID 33013406, 2020). "For example, miR-34a can bind to the 3′-UTR of Notch1 and Jagged1 in colon cancer cells and cervical cancer cells, thus inhibiting the cell migratory ability and the expression of vimentin and fibronectin, and promoting the expression of E-cadherin." (PMID 30781524, 2019). "Our study has revealed that JSD can significantly upregulate E-cad and downregulate N-cad, Vimentin, Snail, Slug and Twist1 in colon cancer cells, leading to a reversion of EMT." (PMID 31772677, 2019). "Based on this reasoning, we posit that modulation of beta-subunits composition by increasing of TUBB4B in colon cancer cells undergoing EMT can affect microtubule colocalization with vimentin." (PMID 31375012, 2019). "Consistent with our observation, treatment with 5-Aza-Deoxycytidine, a methylation inhibitor, resulted in several folds increase of vimentin mRNA expression in different colon cancer cell lines." (PMID 29925392, 2018). "In vitro, LINC00959 knockdown enhanced colon cancer cell proliferation, invasion, and migration; upregulated N-cadherin and vimentin; and downregulated E-cadherin and Caspase-3." (PMID 29228592, 2017).
colon carcinoma (continued). "Markers that indicate EMT in tissues are sparse, and detection of typical EMT markers such as ZEB1, SNAIL1, or Vimentin is difficult in primary colon cancers, as reflected by few convincing in situ studies." (PMID 27120783, 2016). "Although vimentin methylation was detected in the majority of colon cancers we found a statistically significant increase in level of methylated vimentin in patients with CIMP-high CRC, P < 0.001." (PMID 27542211, 2016). "In colon cancer cell lines (HT-29 and SW-620) miR-133b was shown be essential for the inhibitory effects of TAp63 on RhoA, E-cadherin and vimentin, the authors concluded that miR-133b is able to suppress the metastasis of colon cancer." (PMID 27092493, 2016). "Not surprisingly, eIF5A2 upregulation significantly reduced the expression of E-cadherin and enhanced vimentin expression in the four colon cancer cell lines." (PMID 26581310, 2015). "Another biomarker for colon cancer is the fecal detection of aberrant methylation of Vimentin gene (VIM)." (PMID 25215506, 2014). "To assess the relationship between Wnt3a and EMT in colon cancer, we investigated the expression of the EMT-associated markers E-cadherin, vimentin, and β-catenin (also a marker of Wnt/β-catenin pathway activation)." (PMID 25499541, 2014). "In human colon cancer tissue samples, lower levels of E-cadherin expression, as well as higher levels of vimentin expression and β-catenin nuclear distribution, were observed in the Wnt3a strong group than in the weak and negative expression groups." (PMID 25499541, 2014). "Of note, these authors demonstrated that TGFβ-1-mediated EMT directly drives vimentin production in colon cancer cells." (PMID 21747928, 2011). "Interestingly, the expression of N-Cadherin, Vimentin, Slug, and Snail was down-regulated in both colon cancer cell lines at concentrations of 4 μM and 8 μM of minocycline." (PMID 40471394, 2025). "Furthermore, western blot experiments also showed that SERPINC1 regulates the migratory capacity of colon cancer cells by regulating the expression of VIM and Cdh1 in colon cancer cells." (PMID 38923313, 2024). "Western blotting showed that TGF‐β could promote the expression of VIM and inhibit the expression of Cdh1 in colon cancer cells." (PMID 38923313, 2024). "Moreover, the targets of miR-34 can be molecules responsible for tumor proliferation and invasion, as well as epithelial-mesenchymal transition (EMT) (vimentin and E-cadherin in bladder and colon cancer models)." (PMID 36986829, 2023). "Moreover, IL-17 augmented the expression of vimentin, CyclinD1, and cyclinE, while attenuating the expression of E-cadherin in colon cancer cells." (PMID 38105184, 2023). "The inhibition of ALBU and HNF4 expression, as well as the observed morphological changes associated with the modulation of Vimentin and CK8/18, can be ascribed to TGFβ1 activity, which is known to be carried by EVs, including those released by colon cancer cells." (PMID 37072829, 2023). "Soluble vimentin was detected at higher levels in the sera of colon cancer patients, suggesting that it might represent a potential disease biomarker." (PMID 35892334, 2022). "However, the overexpression of SALL4 accelerated the invasion and proliferation of colon cancer cells, which was manifested as downregulation of E-cadherin and upregulation of N-cadherin, vimentin, and Twist." (PMID 35692499, 2022). "STP could specifically bind with vimentin highly expressed on the surface of colon cancer cells, thus increasing the tumor-targeting effects of STP-mNPs/DOX." (PMID 34721033, 2021). "Moreover, a reduction in protein expression levels of phospho-Rac1/Cdc42/Rac1/Cdc42 ratio, Cofilin, Vimentin, and phospho-Paxillin was found in both colon cancer cell lines studied." (PMID 32143529, 2020).